ZEB1 (zinc finger E-box binding homeobox 1)
Diseases named in the same sentence as ZEB1 in open-access papers (continued):
Sharing a sentence is not in itself a finding about the gene and the disease.
cancer (continued). "Moreover, metformin suppresses the AKT/mTOR/ZEB1 signaling pathway via the inhibition of the TGF-β1-induced EMT-like process in GBM cancer stem cells." (PMID 36402997, 2022). "Aggressive cancer cells exhibit sustained high levels of ZEB1/2." (PMID 36140527, 2022). "ZEB1 plays a critical role in facilitating tumorigenesis and cancer cell distant metastasis." (PMID 36273188, 2022). "Additionally, BHMPS effectively decreased the levels of serum-stimulated EMT-activating transcription factors, including Snail, Slug, Zeb1, and Twist1, which are highly related to cancer migration and invasion." (PMID 35053535, 2022). "Importantly, FGF1 expression was positively associated with ZEB1 and TWIST1 expression in pan-cancers." (PMID 35864158, 2022). "In addition, overexpression of EMT-TFs, e.g., Twist1, Zeb1, or Snai1, can also confer the stem cell traits to normal and transformed epithelial cells as well as cancer cells 19,53-55." (PMID 36276640, 2022). "This implies that the phenotypic changes other than EMT induced by ZEB1 may contribute to Erlotinib resistance at the Pan-cancer scale." (PMID 35618721, 2022). "Contrastingly, Zeb1 expression increased significantly in mouse embryonal carcinoma cells." (PMID 35611144, 2022). "BRG1 interacts with ZEB1 at the N-terminal region, in the invasive front of carcinomas." (PMID 35454770, 2022). "It is well known that ZEB1 is a key activator of the EMT process in cancer cells." (PMID 34814869, 2021). "Furthermore, Zeb1 has been shown to be a crucial regulator for acquisition of EMT-like and stemness phenotypes in cancer cells, with the mechanism featuring a self-enforcing CD44s/Zeb1 feedback loop." (PMID 33822772, 2021). "In addition, increasing evidence suggests that ZEB1-mediated EMT is an important process affecting the cancer sensitivity to chemotherapeutics." (PMID 34439151, 2021). "ZEB1, a transcription factor, is overexpressed in several human cancers, including OC." (PMID 33641229, 2021). "Since ZEB1 is an important regulator of EMT and cancer metastasis, we explored whether the ZEB1-PFKM axis also functions in HCC cell migration, invasion and metastasis." (PMID 33897890, 2021). "ZEB1 is correlated with resistance to various drugs in many types of cancer." (PMID 33768509, 2021). "It is well established that Zeb1 mediates resistance to anti-cancer therapy." (PMID 34074001, 2021). "When overexpressed from lentiviral vectors in TSU and HOC313 cells, which express endogenous EHF-SF only at low levels, the EHF-SF-L285P mutation no longer downregulated ETS1 and ZEB1, inhibited motility, and sensitized cells to anti-cancer drug." (PMID 33712555, 2021). "Therefore, ZEB1 expression is correlated with both cancer aggressiveness and with the responses of cancer to butyrate." (PMID 33768509, 2021). "We also identify that the genetic loss of Snail and Twist (associated with suppression of Zeb1) substantially affects the plastic continuum of the EMT program and stabilizes the epithelial phenotype with a shift toward epithelial cancer cells, away from the pEMT and mesenchymal states." (PMID 33852841, 2021). "Zinc‐finger E‐box‐binding homeobox 1 (ZEB1) is a crucial EMT inducer in various human cancers." (PMID 33764690, 2021). "Abundant evidence shows that Zeb1 regulates stem cell properties in cancer, including self-renewal." (PMID 33108352, 2021). "PTBP3 directly regulates the EMT process and cancer stem cells by binding to the 3′UTR of ZEB1." (PMID 34944712, 2021).
cancer (continued). "MiR-205 was shown to target the ZEB1 gene which is known to induce EMT in various cancers." (PMID 34295245, 2021). "Moreover, ZEB1 initiates chemoresistance but inhibits the apical–basal polarity of cancer cells and antiestrogen sensitivity." (PMID 35008529, 2021). "Decreased levels of miR-205-5p expression in CTC+ samples allow higher expression of the ZEB1 gene, which could contribute to better condition and protection of cancer cells by several processes as previously discussed." (PMID 35008529, 2021). "ZEB1 is a crucial inducer of EMT to promote the metastasis of cancer cells, but whether its stability is regulated by USP39 or TRIM26 in HCC remains enigmatic." (PMID 33649471, 2021). "Herein, we show that the cancer-associated RNA chaperone La is required for TGFβ-induced EMT, elevated expression of transcriptional EMT master regulator ZEB1, and supports cancer stem cell properties as indicated by higher CSC marker expression and increased sphere formation and growth." (PMID 33477794, 2021). "ZEB1 is a master transcription factor that activates the EMT process in various cancers." (PMID 33833131, 2021). "Overall, circ_KIAA1429 could promote HCC progression through the m6A-YTHDF3-Zeb1 pathway to stabilize Zeb1 expression, which may represent a new target in cancer treatment." (PMID 33731118, 2021). "Here, we show that Zeb1—a transcription factor known for its pivotal role in epithelial-mesenchymal transition, cell plasticity, and metastasis in cancer—is expressed at low levels in epithelial cells of the pancreas and is crucial for organogenesis and pancreas function." (PMID 34112759, 2021). "Additionally, DHRS4-AS1 inhibited the expression of epithelial-mesenchymal transition (EMT)-related factors, N-cadherin, ZEB1, and Vimentin but increased E-cadherin expression in the cancer stem cell spheres." (PMID 33425890, 2020). "Consequently, ZEB1 stimulates PD-L1 to protect cancer cells against the cytotoxic effects of immune cells, resulting in promoting the survival and migration of DLBCL cells." (PMID 32664703, 2020). "Interestingly, ZEB1 mRNA levels showed a significant increase for the given time periods (12 and 24 h) in all three cancer cell lines." (PMID 33097763, 2020). "While our study requires further validation, our results suggest that reagents targeting the DAXX/ZEB1 pathway could help decrease cancer cell motility and invasiveness and thus prevent metastasis in CRC." (PMID 31942198, 2020). "Additionally, inhibition of ZEB1 by miRs such as miR-101-3p, miR-525-5p and miR-186-5p is also corelated with a diminution in metastasis of cancer cells due to EMT inhibition by E-cadherin up-regulation." (PMID 32664703, 2020). "ZEB1 is expressed in most human cancers in epithelial tissues." (PMID 32810922, 2020). "Regarding the role of ZEB1 as a transcription factor of EMT, however, our findings suggest that induction of ZEB1 could be an independent mechanism of the EMT since only ZEB1 showed consistent induction in all three cancer cell lines." (PMID 33097763, 2020). "Additionally, the increased expression of ZEB1 enhanced the chemo/radioresistance of cancer cells, indicating that ZEB1 is not only involved in the oncogenesis and development of cancers but also affects the prognosis of cancer patients." (PMID 32014049, 2020). "Therefore, in addition to normal treatments for cancers, the exploration of ZEB1 in immunotherapy has provided new potential and effective therapeutic strategies for metastatic breast cancers." (PMID 32014049, 2020). "Ultimately, our findings confirmed that miR-4269 served as a cancer suppressor in PC through regulation of ZEB1/OTX1 pathway, which suggested that miR-4269 might represent a promising target for the clinical treatment of PC." (PMID 32484209, 2020).
cancer (continued). "However, miR-200c is also one of the essential repressors of ZEB1 in cancer cells, since it binds directly to the 3’UTR region of ZEB1 mRNA and enhances its degradation." (PMID 32570918, 2020). "ZEB1 stimulates the migration and invasion of cancer cells through the EMT transition." (PMID 32667627, 2020). "Similarly, in lung adenocarcinoma (LUAD) cells, miR-665 is able to inhibit cancer metastasis via ZEB1 down-regulation." (PMID 32664703, 2020). "Moreover, Orai1 is capable of endowing non-tumorigenic immortalized oral epithelial cells with self-renovation, and concurrently enhances transcribing pluripotent and cancer stem cells-associated agents such as Nanog, Sox2, KLF4, Oct4, Zeb1, Bmi1, and Zeb2." (PMID 32280305, 2020). "Taken together, the miR/ZEB1 axis is an important factor in cancer dissemination and may be an important and relevant target in cancer therapeutics." (PMID 32664703, 2020). "The effect of lncRNAs on miR/ZEB1 axis has been investigated in cancer cells." (PMID 32664703, 2020). "Indeed, H19 sponges miR-200a or miR-200b/c to promote cancer metastasis through ZEB1 and ZEB2 upregulations." (PMID 32610610, 2020). "MiR-200a was found to down-regulate ZEB1 in suppressing cancer cell migration." (PMID 32664703, 2020). "A growing body of publications has considered ZEB1 in normal and cancer cells to be a crucial regulator of fundamental intracellular processes as well a major denominator of plasticity, driving drug adaptation and phenotypic resistance to various types of anticancer therapy." (PMID 32266287, 2020). "We next examined whether USP51 depletion could inhibit cancer cell metastasis through the regulation of ZEB1." (PMID 32296027, 2020). "However, in cancer conditions, TGF-β and ZEB1 cooperate with each other to promote migration of cancer cells." (PMID 32664703, 2020). "Considering the interesting expression pattern of Zeb1 in the prostate epithelium and the previously reported role of Zeb1 in stemness acquisition and maintenance of cancer stem cells (CSC) characteristics, we decided to investigate the biological relevance of Zeb1+ basal cells in the prostate." (PMID 32024836, 2020). "Destruction of the junction between ZEB1 and the mentioned chromatin-modifying enzymes may represent an effective method of treating cancer." (PMID 33392180, 2020). "Moreover, Zeb1 was required for stemness and metabolic plasticity of the cancer cells in a mouse model of PDAC." (PMID 33297508, 2020). "YB1 is a transcription factor that can enhance the expression of ZEB1 in cancer." (PMID 32664703, 2020). "To further study the participation of P2X7R in the epithelial-to-mesenchymal transition (EMT), we assessed the effect of stimulating 4T1 cancer cells with BzATP on the expression of genes associated with the mesenchymal (SNAI1, ZEB1, TWIST) or the epithelial (ZO1, CDH1) phenotypes." (PMID 32825056, 2020). "A recent study has identified the presence of ZEB-1 mRNA in cancer cell-derived exosomes." (PMID 32600257, 2020). "Expression of Zeb1 by cancer cells endows them with a more aggressive phenotype, including enhanced invasive capacities, therapeutic resistance, and stemness, resulting in poor clinical outcomes in a variety of human cancer types." (PMID 33322354, 2020). "In an attempt to establish a link between EMT and LD accumulation, both being promoted by acidosis-driven TGF-β2 signaling, we could document that silencing ZEB1 blocked EMT in 6.5/cancer cells but also reduced the formation of LD under acidosis." (PMID 31974393, 2020). "Notably, miR-429 can inhibit the metastasis of cancer cells and stimulate apoptotic cell death through ZEB1 down-regulation." (PMID 32664703, 2020). "Moreover, underlying mechanisms should be investigated for individual context, as the roles of ZEB1 and other transcriptional factors are highly treatment- and cancer type-dependent." (PMID 32266287, 2020).
cancer (continued). "Notably, within tumors, high Zeb1 expression is restricted to a subpopulation of stem-like malignant cells at the invasive front, where cancer cells interact with their microenvironment." (PMID 33046710, 2020). "It was known that TGF‐β1 and ZEB1 can regulate the EMT process of various cancer cells." (PMID 32227618, 2020). "In addition, we reveal that ET-1/ETAR pathway is an integral signaling cue of this double ZEB1/miR-200 feedback loop, suggesting a more complex regulation pattern controlling cancer progression." (PMID 33188287, 2020). "This in turn promotes up-regulation of ZEB1 and enhanced metastasis of cancer cells." (PMID 32664703, 2020). "We show here the appearance of ectopic ZEB1 protein in keratinocytes of dysplastic epidermis, thus providing a link between low-dose irradiation of holoclone keratinocyte precursor cells and potential initiation sites of the carcinoma development cascade." (PMID 32824646, 2020). "We then asked whether the robust increase of ZEB1 also exists near the M-end of the EMT path in cancer cells, and we compared the distributions of ZEB1 expression across the five cancer cell clusters along the EMT paths." (PMID 32038999, 2019). "Furthermore, YAP was shown to cooperate with EMT master factor ZEB1 in the activation of the ZEB1-dependent cancer-promoting gene expression." (PMID 31601778, 2019). "Several studies have revealed that ZEB1 could upregulate the expression of PD-L1 to contribute to the immune evasion in cancer cells." (PMID 31570691, 2019). "It remains unclear, however, why expression of ZEB1/2 is sustained at high levels in aggressive cancer cells." (PMID 31682640, 2019). "We observed that PyMT-cancer cells grew at a comparable rate in the presence of control and ZEB1-deleted CAFs at 18, 24 and 48 h of culture, suggesting that the defect in cell invasion was not due to proliferation deficiency in the cells at least within 48 h of culture." (PMID 31324807, 2019). "Transcription factor ZEB1 is known to be a master regulator of EMT process in varied cancer types." (PMID 31019894, 2019). "Formerly, several works argued that ZEB1 could upregulate the expression of PD-L1 in cancer cells and contribute to the inactivation of CD8+ T cells." (PMID 31570691, 2019). "ZEB1 expression is abnormally upregulated in various types of human cancer, including thyroid, cervical, gastric, endometrial, and prostate cancers." (PMID 30846940, 2019). "Moreover, decreased expressions of mesenchymal transcription factors Zeb1 and Zeb2 were observed in cancer cells treated with MBCD as compared to untreated cells." (PMID 30625181, 2019). "Accumulating evidence shows that ZEB1 has crucial roles during cancer initiation and progression." (PMID 30846940, 2019). "In addition, miR-128-3p and miR-873-5p were identified to make cancer cells more responsive to anti-cancer agents by suppressing ZEB1 expression." (PMID 31861937, 2019). "Interestingly, a previous study revealed that the expression levels of EMT proteins, such as vimentin and ZEB1, were also decreased in miR-139 transfected cancer cells." (PMID 31426807, 2019). "CCL8-mediated TAM infiltration contributes to hypoxic ZEB1-related cancer progression." (PMID 31263103, 2019). "As with the previous reports that several EMT‐related transcription factors were upregulated in the EMT induction in cancer developments, in this #1 AC, ZEB1 was the most and significantly upregulated gene by the DNA microarray analysis in the EMT‐related transcription factors." (PMID 31674718, 2019). "Moreover, cholesterol treatment inverted metformin-repressed expressions of several cancer-associated genes (e.g., Bcl-xL BCL2, Zeb1, vimentin, BMI1)." (PMID 30625181, 2019). "Based on the observation of upregulated EMT and associated key signature genes such as TGFB2, TGFBR2, SMAD2, and ZEB1 in the high-risk patients, we infer that m6A regulatory machinery must interact with EMT to regulate cancer metastasis in various human malignancies." (PMID 31069256, 2019).
cancer (continued). "LA supplementation strongly decreased TGFβ-induced Zeb1 staining in cancer cells." (PMID 31752242, 2019). "As ZEB1 is implicated in the activation of EMT, downregulation of ZEB1 by silymarin might inhibit the metastasis of cancer cells." (PMID 31126043, 2019). "The important role of Zeb1 in EMT regulation has been described for many cancer types." (PMID 30979372, 2019). "Thus, it is essential to further investigate the clinical features and therapeutic implications of ZEB-1 expression in carcinomas." (PMID 31248382, 2019). "Previous studies show that ERG regulates the expression of frizzled class receptor 4, E-cadherin, vimentin, ras homolog family member A, vascular endothelial growth factor receptor 2, and zinc finger E-box binding homeobox 1/2 during cancer metastasis and epithelial–mesenchymal transition process." (PMID 29773901, 2018). "It has been reported that ZEB-1 could promote DNA repair and lead to radioresistance in cancer cells." (PMID 30393570, 2018). "We next further determined whether Akt and Zeb1 are involved in the stimulatory effect of cancer-cell invasion." (PMID 29615080, 2018). "This role of ZEB1 has been further confirmed using cancer cell lines." (PMID 32309604, 2018). "ZEB1 has also been shown to repress several other miRNAs, such as miR-203 and miR-183, which cooperatively repress stem cell factors and inhibit the stemness property in cancer cells and mouse embryonic stem cells." (PMID 29958433, 2018). "However, the level of Zeb1 was still sufficient to maintain repression of Zeb2, allowing the cancer cells to respond to Tgf-β1 accumulating at sites of inflammation and airway invasion to re-establish Zeb1hi and EMT in the invading cells." (PMID 29930325, 2018). "In addition to E-Cadherin, ZEB1 exhibits transcriptional control over other target genes that play roles in cancer progression." (PMID 32309604, 2018). "Zeb1, a zinc-finger homeodomain transcription factor, actively facilitates EMT by transcriptional inhibition of the cell–cell adhesion molecule E-cadherin, a hallmark of the initiating step of cancer metastasis." (PMID 29988033, 2018). "Therefore, the EMT process that is associated with the expression of E-cadherin, vimentin, ZEB1 and ZEB2 is generally used to indicate the ability of cancer cell metastasis and invasion." (PMID 29559853, 2018). "In recent years there has been an accumulation of evidence with regard to ZEB1 in various cancers." (PMID 32309604, 2018). "Importantly, activation of OCT4 signaling and upregulation of EMT inducer ZEB1 induce PD-L1 expression in cancer cells, thereby suggesting a possible immune evasion mechanism employed by cancer stem cells during metastasis." (PMID 30283733, 2018). "This review seeks to shed light on the complexity of ZEB1 with respect to cancer." (PMID 32309604, 2018). "This study unveiled an unexpected role for ZEB1 beyond cell differentiation and cancer." (PMID 30304480, 2018). "Thus, it appears that the Zeb1/CD44 loop evident in CGC is disrupted by stable Zeb1-independent repression of CD44 that is initiated as cancer cells are generated." (PMID 29930325, 2018). "While at first glance these results may appear unexpected, further reflection on the duality of ZEB1’s nature as activator and suppressor would suggest that it is able to affect divergent functions in both normal and cancer cells." (PMID 32309604, 2018). "ZEB1’s ability to be a transcriptional repressor or a transcriptional activator goes beyond what has been seen in normal regulatory processes, being also found within dysregulated processes such as cancer." (PMID 32309604, 2018).